TBL3 (transducin beta like 3)
Description:
Part of the small subunit (SSU) processome, first precursor of the small eukaryotic ribosomal subunit. During the assembly of the SSU processome in the nucleolus, many ribosome biogenesis factors, an RNA chaperone and ribosomal proteins associate with the nascent pre-rRNA and work in concert to generate RNA folding, modifications, rearrangements and cleavage as well as targeted degradation of pre-ribosomal RNA by the RNA exosome.
Synonyms: SAZD; UTP13
Tractability: Small molecule: a structure with a bound ligand is known. PROTAC: UniProt records ubiquitination sites on it; ubiquitination databases record sites on it; its protein half-life has been measured.
Gene: Protein-coding gene on chromosome 16 (1,972,050 to 1,982,929, forward strand). Ensembl gene ENSG00000183751.
Subcellular location: Nucleus, nucleolus
Subcellular location (Human Protein Atlas): Nucleoli
Pathways (Reactome):
Metabolism of RNA: Major pathway of rRNA processing in the nucleolus and cytosol; rRNA modification in the nucleus and cytosol
Gene Ontology:
Molecular function: protein binding; RNA binding; U3 snoRNA binding
Biological process: ribosomal small subunit biogenesis; endonucleolytic cleavage in 5'-ETS of tricistronic rRNA transcript (SSU-rRNA, 5.8S rRNA, LSU-rRNA); endonucleolytic cleavage to generate mature 5'-end of SSU-rRNA from (SSU-rRNA, 5.8S rRNA, LSU-rRNA); maturation of SSU-rRNA; rRNA processing
Cellular component: nucleolus; small-subunit processome; 90S preribosome; nucleoplasm; Pwp2p-containing subcomplex of 90S preribosome
Genetic constraint (gnomAD): Loss-of-function variants: 71 observed, 97.77 expected, observed/expected ratio (o/e) 0.73, 90% interval 0.6 to 0.88. The synonymous counts are far from expectation, so gnomAD's model fits this gene poorly and the ratio says little. Missense variants: 1,188 observed, 1,089.4 expected, observed/expected ratio (o/e) 1.09, 90% interval 1.04 to 1.14. Synonymous variants: 578 observed, 471.46 expected, observed/expected ratio (o/e) 1.23, 90% interval 1.14 to 1.31.
Homologues: Orthologues: chimpanzee TBL3 (99% identical), macaque TBL3 (97% identical), guinea pig TBL3 (89% identical), mouse Tbl3 (88% identical), rat Tbl3 (88% identical), dog TBL3 (88% identical), pig TBL3 (86% identical), tropical clawed frog tbl3 (62% identical), zebrafish tbl3 (53% identical), Drosophila melanogaster CG1671 (32% identical), Caenorhabditis elegans Y53C12B.1 (31% identical). Paralogues in human: GNB1L (9% identical).
Diseases named in the same sentence as TBL3 in open-access papers:
TBL3 is named in the same sentence as 8 diseases in open-access papers, as found by Europe PMC text mining. Sharing a sentence is not in itself a finding about the gene and the disease. The quoted sentences say what the papers report.
renal carcinoma (1 paper, 2022). A carcinoma arising from the epithelium of the renal parenchyma or the renal pelvis. "In accordance, in renal cancer a high protein level of TBL3 is also associated with a favorable prognosis." (PMID 35409174, 2022).
Sepsis (1 paper, 2024). Sepsis is defined as life-threatening organ dysfunction caused by a dysregulated host response to infection. "The current mechanism of action of WDR75 and TBL3 in patients with sepsis is unclear, and further studies are needed." (PMID 39438952, 2024).
cancer (2 papers, 2022 to 2024). A tumor composed of atypical neoplastic, often pleomorphic cells that invade other tissues. "In addition, EXOSC5, UTP14A, TWISTNB, and TBL3 were closely related to the occurrence or prognosis of several cancers." (PMID 35601016, 2022).
infection (2 papers, 2013 to 2023). The state of being infected such as from the introduction of a foreign agent such as serum, vaccine, antigenic substance or organism. "To investigate the molecular mechanisms underlying the phenotypes of Theileria-infected cells, we studied TBL3 cells which were derived by in vitro infection with T. annulata of BL3 cells, an immortalized, bovine B lymphocyte cell line." (PMID 23637592, 2013).
tumor (2 papers, 2022 to 2023). "This category likely represents tumour suppressors and were more than pro-tumorigenic genes (only two genes) shared between TBL3, TBL20 and attenuated Beja (i.e., nine genes)." (PMID 37875584, 2023).
adenocarcinoma (1 paper, 2014). A common cancer characterized by the presence of malignant glandular cells. "In 27 adenocarcinomas of never smokers, only three genes, EGFR, TBL3 and HSD17B7P2, occurred in two or more samples." (PMID 24894543, 2014).
TBL3 also shares sentences with these, for which no sentence is quoted: COVID-19 (1 paper); Insulin resistance (1).